ANXA11 (annexin A11)
Diseases named in the same sentence as ANXA11 in open-access papers (continued):
Sharing a sentence is not in itself a finding about the gene and the disease.
amyotrophic lateral sclerosis (27 papers, 2019 to 2025). Amyotrophic lateral sclerosis (ALS) is a neurodegenerative disease characterized by progressive muscular paralysis reflecting degeneration of motor neurons in the primary motor cortex, corticospinal tracts, brainstem and spinal cord. "Annexin A11 (ANXA11) has emerged as a significant gene associated with amyotrophic lateral sclerosis (ALS) and cognitive impairments." (PMID 40690048, 2025). "Annexin A11 tethers mRNA to lysosomes for transport in neurons, and mutations disrupting this function are associated with amyotrophic lateral sclerosis in humans." (PMID 40411591, 2025). "AnxA11 has recently become a major focus in amyotrophic lateral sclerosis research, especially after genetic studies identified mutations in the ANXA11 gene." (PMID 40350993, 2025). "Mutations in ANXA11 are associated with the fatal neurodegenerative disorder amyotrophic lateral sclerosis (ALS)." (PMID 38639785, 2024). "We examine the pathogenicity of a novel VUS P93S in Annexin A11 (ANXA11) – an amyotrophic lateral sclerosis/frontotemporal dementia‐associated gene – in a corticobasal syndrome kindred." (PMID 38923692, 2024). "ANXA11 has previously been associated with amyotrophic lateral sclerosis and frontotemporal dementia." (PMID 37886540, 2023). "The P93S VUS is located within the low complexity domain (LCD), a region of ANXA11 in which previously identified amyotrophic lateral sclerosis/frontotemporal dementia mutations reside." (PMID 37886540, 2023). "In conclusion, we describe a family with a novel clinical presentation and a novel VUS in the amyotrophic lateral sclerosis/frontotemporal dementia associated gene, ANXA11." (PMID 37886540, 2023). "Korean patients diagnosed with amyotrophic lateral sclerosis (n = 882) underwent genetic evaluations through next-generation sequencing, which identified 16 ANXA11 variants in 26 patients." (PMID 36458208, 2022). "This study investigated the clinical aspects of sporadic amyotrophic lateral sclerosis patients carrying ANXA11 variants and verified the pathogenicity of the hotspot variants associated with amyotrophic lateral sclerosis-frontotemporal dementia." (PMID 36458208, 2022). "Recently, mutations in ANXA11 have been reported in patients with amyotrophic lateral sclerosis and multisystem proteinopathy." (PMID 36134701, 2022). "Mutations in annexin A11 are a rare cause of amyotrophic lateral sclerosis." (PMID 38989900, 2025). "Mutations in the proline-rich domain (PRD) of annexin A11 are linked to amyotrophic lateral sclerosis (ALS), a fatal neurodegenerative disease, and generate abundant neuronal A11 inclusions by an unknown mechanism." (PMID 37433222, 2023). "Therefore, we studied the clinical aspects of sporadic amyotrophic lateral sclerosis patients carrying ANXA11 variants." (PMID 36458208, 2022). "Increasing genetic evidence supports the hypothesis that variants in the annexin A11 gene (ANXA11) contribute to amyotrophic lateral sclerosis pathogenesis." (PMID 36458208, 2022). "In addition, functional studies using amyotrophic lateral sclerosis-frontotemporal dementia patient fibroblasts revealed that the ANXA11 variants p.P36R and p.D40G impaired intracellular calcium homeostasis, stress granule disassembly and protein translation." (PMID 36458208, 2022). "Interestingly, amyotrophic lateral sclerosis (ALS)-linked mutation in annexin A11 reduced its association with LAMP1-postive compartments in neurons, rendering the formation of more stable and possibly aggregation-prone RNA granules." (PMID 34178987, 2021). "Mutations in AnxA11 have been linked to amyotrophic lateral sclerosis (ALS)." (PMID 32344647, 2020). "Annexin A11 mutations are a rare cause of amyotrophic lateral sclerosis (ALS), wherein replicated protein variants P36R, G38R, D40G and D40Y are located in a small helix within the long, disordered N-terminus." (PMID 38989900, 2025).
amyotrophic lateral sclerosis (continued). "ANXA11 has also been linked to amyotrophic lateral sclerosis (ALS), an incurable progressive motor neuron disease." (PMID 38516187, 2024). "Mutations in ANXA11 cause amyotrophic lateral sclerosis (ALS) and have recently been identified as a cause of multisystem proteinopathy and adult‐onset muscular dystrophy." (PMID 36651622, 2023). "ANXA11, on the other hand, has been shown to be associated with amyotrophic lateral sclerosis (ALS)." (PMID 36358945, 2022). "This study suggests that the clinical manifestations of amyotrophic lateral sclerosis and amyotrophic lateral sclerosis-frontotemporal dementia spectrum patients with ANXA11 variants could be distinctively characterized depending upon the location of the variant." (PMID 36458208, 2022). "Strikingly, AnxA11 mutations associated with amyotrophic lateral sclerosis (ALS) disrupted docking between RNA granules and lysosomes, thus hampering neuronal RNA granule transport." (PMID 35071237, 2021). "Recent studies have revealed that mutations in AnxA11 play an important role in the development of the neurodegenerative disease amyotrophic lateral sclerosis (ALS)." (PMID 32344647, 2020). "RNA granule transport requires ANXA11, and amyotrophic lateral sclerosis (ALS)-associated mutations in ANXA11 impair RNA granule transport by disrupting their interactions with lysosomes." (PMID 31539493, 2019). "The known disease-associated Annexin A11 (ANXA11) mutations result in ANXA11 aggregation, alterations in lysosomal-RNA granule co-trafficking, and TDP-43 mis-localization and present as amyotrophic lateral sclerosis or frontotemporal dementia." (PMID 37886540, 2023). "Expression of the P93S ANXA11 variant causes abnormalities in TDP-43 expression and function, which are hallmarks of amyotrophic lateral sclerosis/frontotemporal dementia pathophysiology." (PMID 37886540, 2023). "Moreover, amyotrophic lateral sclerosis (ALS)-associated mutations in ANXA11 disrupted the docking of RNA granules to lysosomes and impaired RNA granule transport, suggesting that disrupted membranous RNA transport could contribute toward ALS neuropathy and pathogenesis." (PMID 34336865, 2021). "Finally, Anxa11 mutations were found in the rare and related neurodegenerative diseases amyotrophic lateral sclerosis (ALS) and frontotemporal dementia." (PMID 33810523, 2021). "The Annexin A11 (ANXA11) gene has been newly identified as a causative gene of amyotrophic lateral sclerosis (ALS) with or without frontotemporal dementia (FTD)." (PMID 36226077, 2022).
frontotemporal dementia (8 papers, 2019 to 2025). Frontotemporal dementia (FTD) comprises a group of neurodegenerative disorders, characterized by progressive changes in behavior, executive dysfunction and language impairment, as a result of degeneration of the medial prefrontal and frontoinsular cortices. "Subsequent independent studies identified these and other ANXA11 variants in association with familial forms of frontotemporal dementia (FTD), fitting the rubric of genes causing a spectrum of disease from ALS to FTD." (PMID 38923692, 2024). "Recent research has revealed that TDP-43 interacts with annexin A11 (ANXA11) to form heteromeric amyloid filaments in frontotemporal lobar degeneration with TDP-43 inclusions (FTLD-TDP) Type C." (PMID 39940966, 2025). "Finally, we found abundant annexin A11 inclusions as the primary pathologic finding in a case of progressive supranuclear palsy-like frontotemporal dementia with prominent striatal vacuolization due to a novel variant, ANXA11 p.P75S." (PMID 38896345, 2024). "Mutations in ANXA11 cause ALS and a related neurodegenerative disorder, frontotemporal dementia (FTD)." (PMID 31539493, 2019). "Finally, we report a novel ANXA11 p.P75S variant in a case of progressive supranuclear palsy-like FTD syndrome, previously diagnosed neuropathologically as frontotemporal lobar degeneration with TDP-43, tau and alpha-synuclein-negative, ubiquitin-positive inclusions (FTLD-U)." (PMID 38896345, 2024).
autoimmune disease (6 papers, 2012 to 2023). A disorder resulting from loss of function or tissue destruction of an organ or multiple organs, arising from humoral or cellular immune responses of the individual to their own tissue constituents. "The protein encoded by ANXA11 is a 56-kD antigen recognized by sera in patients with various autoimmune diseases, as reviewed in." (PMID 36824606, 2023). "Of interest, and not surprising, is the fact that multiple mutations present in Anxa11 are increasingly being identified in various autoimmune diseases." (PMID 36233010, 2022). "SNPs in ANXA11 have also been reported to be associated with autoimmune diseases." (PMID 37250650, 2023). "Besides the link of several annexins, including AnxA11, to the autoimmune disease SLE, Anxa11 polymorphism were found in other autoimmune disorders, such as granulomatous disease." (PMID 33810523, 2021). "In addition, anti-Anxa11 autoantibodies have been proposed to enhance the vulnerability to inflammatory or autoimmune disorders by interfering with Anxa11’s ability to regulate apoptosis." (PMID 36233010, 2022). "Our study did not detect an association of previously identified autoimmune disease risk SNPs (rs2358817 within VTCN1 gene; rs1049550 within ANXA11 gene; rs6679356 within IL12RB2 gene andrs9865818 within LPP gene) with T1DM in Croatian T1DM trio families." (PMID 23152861, 2012).
hepatocellular carcinoma (6 papers, 2012 to 2024). A malignant tumor that arises from hepatocytes. "LncRNA AGAP2-AS1, functioning as a ceRNA, up-regulates the expression of ANXA11 via binding with miR-16-5p and promotes cell proliferation and metastasis in hepatocellular carcinoma." (PMID 31737900, 2020). "Furthermore, AGAP2-AS1 promotes cell proliferation, migration, invasion, and EMT progression in hepatocellular carcinoma via AGAP2-AS1/miR-16-5p/ANXA11/AKT axis as ceRNA." (PMID 32960785, 2020). "In hepatocellular carcinoma, the overexpression of ANXA2, ANXA3, ANXA4, ANXA5 and ANXA11 promotes proliferation because ANXA2–ANXA5 affect Wnt/β-catenin, MEK-ERK, PI3K/AKT-HIF-α and other pathways." (PMID 36936694, 2023). "In hepatocellular carcinoma, AGAP2-AS1 is reported to function as a competitive endogenous RNA; it upregulates ANXA11 expression by sponging miR-16-5p and promotes cell proliferation and metastasis." (PMID 33889541, 2021).
colorectal cancer (5 papers, 2008 to 2024). A primary or metastatic malignant neoplasm that affects the colon or rectum. "Upregulation of ANXA11 causes ovarian and colorectal cancer development, recurrence, and treatment resistance." (PMID 38361124, 2024). "Anxa11 was involved in the LNM of colorectal cancer, the drug-resistant capacity of ovarian cancer cells or in the prognosis of ovarian cancer patients." (PMID 26908448, 2016). "Annexin A11 was overexpressed in colorectal cancer and increased expression correlated with more advanced tumour stage." (PMID 18071363, 2008). "Consequently, insights into the precise regulatory mechanisms of the HSF1/LINC00857/ANXA11 axis in colorectal cancer progression can further develop novel specific targeted drugs and diagnostic strategies for colorectal cancer." (PMID 36010849, 2022). "The knockout of ANXA11 attenuated colorectal cancer formation in vivo." (PMID 36010849, 2022). "Targeting the HSF1/LINC00857/ANXA11 axis may provide a valuable therapeutic strategy against colorectal cancer." (PMID 36010849, 2022). "Comparing the expression of annexins in lymph node metastasis with the corresponding primary tumours showed that there was a significant decrease in expression of annexin A11 (P=0.01) in lymph node metastasis compared with corresponding primary colorectal cancers." (PMID 18071363, 2008).
proteinopathies (5 papers, 2023 to 2026). "Altogether these findings suggest an important role of annexin A11 in TDP-43 proteinopathies, and highlight the need for further research into aggregation-prone RBPs." (PMID 40468389, 2025). "The importance of heterotypic protein aggregation in TDP-43 proteinopathies is further supported by the co-assembly of TDP-43 with ANXA11 in FTLD-TDP type C brains." (PMID 40468389, 2025). "This study identifies annexin A11 aggregation as a consistent feature of FTLD–TDP Type C, and the presence of annexin A11 aggregates in a subset of other TDP-43 proteinopathy neurodegenerative diseases." (PMID 38896345, 2024). "This unique case of vacuolar annexinopathy implicates annexin A11 dysfunction as being sufficient to cause neurodegeneration independent of TDP-43 proteinopathy." (PMID 38896345, 2024). "Besides, colabeling experiments of ANXA11 with the SQSTM1 protein that aggregates in ANXA11 proteinopathies, showed colocalization in sarcoplasmic inclusions in muscle fibers thus supporting common mechanisms." (PMID 36651622, 2023). "Thus, when annexin A11 aggregates are present in non-Type C TDP-43 proteinopathies, its overall distribution matches the underlying TDP-43 proteinopathy in terms of morphology but with generally reduced distribution and severity." (PMID 38896345, 2024). "This other study also reported incomplete colocalization of ANXA11 with TDP-43 inclusions and the presence of an ANXA11 fragment in a small subset of cases of additional TDP-43 proteinopathies." (PMID 39260416, 2024). "When considering the 3–6% of TDP-43 proteinopathy cases with annexin A11 aggregates (i.e., cases without FTLD–TDP Type C and without a pathogenic ANXA11 variant), there is a suggestion that increased proteostatic burden or genetics may be involved." (PMID 38896345, 2024).
Granuloma (4 papers, 2022 to 2025). A compact, organized collection of mature mononuclear phagocytes, which may be but is not necessarily accompanied by accessory features such as necrosis. "A small study found a correlation between a minor allele in the ANXA11 gene and African Americans with fibrotic pulmonary sarcoidosis, and suggested ANXA11 polymorphism may lead to persistence of Th1 and Th17 cells, resistance to apoptosis, and persistence of granuloma." (PMID 38202248, 2023).
ovarian carcinoma (4 papers, 2012 to 2019). A malignant neoplasm originating from the surface ovarian epithelium. "Silencing of annexin A11 was also associated with cisplatin resistance in ovarian cancer cells." (PMID 27071553, 2016). "Both databases showed that ANXA2, ANXA3, ANXA8, and ANXA11 mRNA expression levels were upregulated in ovarian cancer compared with normal tissues, while ANXA5,ANXA6, and ANXA7 mRNA expression levels were downregulated." (PMID 31474227, 2019). "The knockdown of annexin A11 expression reduced cell proliferation and the ability of ovarian cancer cells to form a colony." (PMID 27071553, 2016). "For example, Annexin A11 is directly involved in cell proliferation in ovarian cancer." (PMID 27071553, 2016). "ANXA3 was upregulated in platinum-resistant ovarian cancer, whereas ANXA1 and ANXA11 expression was negatively correlated with paclitaxel and cisplatin resistance in ovarian cancer, respectively." (PMID 31474227, 2019). "In addition, we analyzed the differential mRNA expression levels of Annexins between ovarian cancer and normal ovarian tissues using the GEPIA database, which indicated that ANXA2, ANXA3, and ANXA11 mRNA expression levels were significantly upregulated in ovarian cancer." (PMID 31474227, 2019).
corticobasal syndrome (3 papers, 2023 to 2025). Corticobasal syndrome (CBS) is a rare neurodegenerative disease characterized by multifaceted motor system dysfunctions and cognitive defects such as asymmetric rigidity, bradykinesia, limb apraxia, and visuospatial dysfunction. "Taken together, this kindred and other ANXA11 mutation carrier cases expand the known clinical spectrum of mutations in ANXA11 to include a corticobasal syndrome presentation." (PMID 37886540, 2023). "We further identified additional patients with mutations in ANXA11 and similar clinical presentations from a large neurodegenerative disease cohort, thereby establishing corticobasal syndrome as part of the phenotypic spectrum of ANXA11 mutations." (PMID 37886540, 2023). "Mutations in ANXA11 were found in association with clinically diagnosed corticobasal syndrome, thereby establishing corticobasal syndrome as part of ANXA11 clinical spectrum." (PMID 37886540, 2023). "ANXA11 mutations were linked to corticobasal syndrome cases." (PMID 38923692, 2024). "We identified a novel VUS in ANXA11 (P93S) in a kindred with corticobasal syndrome and unique radiographic features that segregated with disease." (PMID 37886540, 2023). "Here we describe a family with a VUS in ANXA11 resulting in a serine in position 93 in lieu of the canonical proline, denoted by P93S, who present clinically with corticobasal syndrome (CBS), a novel clinical phenotype not previously associated with this gene." (PMID 38923692, 2024). "Here we describe a family with a P93S variant of uncertain significance (VUS) in ANXA11 who present clinically with corticobasal syndrome, a novel clinical phenotype not previously associated with this gene." (PMID 37886540, 2023).
bladder cancer (2 papers, 2021 to 2022). "Moreover, high ANXA11 levels were associated with a higher overall survival in bladder cancer patients, further supporting an oncosuppressor role in this malignancy." (PMID 36247003, 2022). "In bladder cancer, ANXA11 expression levels were decreased in tumor tissue compared to the normal counterpart, and together with other annexins, serves to identify luminal-subtype bladder tumors." (PMID 36247003, 2022). "We also analyzed the possible role of ANXA-L (ANXA4, ANXA9, ANXA10, and ANXA11) in the regulation of luminal bladder cancer." (PMID 34484309, 2021). "The expression of ANXA1, ANXA2, ANXA3, ANXA5, ANXA6, ANXA8, and ANXA13 was closely related to basal-subtype bladder cancer, while the expression of ANXA4, ANXA9, ANXA10, and ANXA11 was closely related to luminal-subtype BC." (PMID 34484309, 2021).
chronic obstructive pulmonary disease (2 papers, 2015 to 2021). A chronic and progressive lung disorder characterized by the loss of elasticity of the bronchial tree and the air sacs, destruction of the air sacs wall, thickening of the bronchial wall, and mucous accumulation in the bronchial tree. "In addition, a genome wide association study of chronic obstructive pulmonary disease identified one SNP in an intron of ANXA11." (PMID 25961286, 2015).
Cognitive impairment (2 papers, 2025). Abnormal cognition is characterized by deficits in thinking, reasoning, or remembering. "However, it is important to mention that the results from patients with PSEN1, SQSTM1, VCP, and ANXA11 mutations highlight distinct patterns of cognitive impairment, reflecting both shared and gene-specific features of neurodegeneration." (PMID 40649976, 2025). "Pathogenic ANXA11 variants are relatively common in ALS and are strongly associated with cognitive impairment." (PMID 40690048, 2025). "The consistent cognitive impairment observed in ANXA11-ALS patients indicates that genetic screening for ANXA11 variants should be prioritized in ALS patients with cognitive symptoms, while comprehensive neuropsychological evaluation must be performed in all identified ANXA11 carriers." (PMID 40690048, 2025). "The clinical features of ALS patients carrying ANXA11 variants remain poorly understood, and cognitive impairment in these patients has not yet been studied in detail." (PMID 40690048, 2025). "All ANXA11-ALS had cognitive impairment compared to 49% of WT-ALS and 60.9% of C9ORF72-ALS." (PMID 40690048, 2025).
dry eye (2 papers, 2015 to 2019). "Different proteins involved with dry eye dysfunction: ANXA1, ANXA11, CST4, PRDX5, PLAA and S100A6; were validated as biomarkers." (PMID 26287192, 2015). "In addition to these extracellular proteins, several intracellular proteins such as Annexin A1 (ANXA1), Annexin A11 (ANXA11), aldehyde hydrogenase 3A1, clusterin, Glutathione-S-transferase P1, have also been shown to be deregulated in tears of dry eye patients." (PMID 30673862, 2019).